ABCG2 (ATP binding cassette subfamily G member 2 (JR blood group))
Diseases named in the same sentence as ABCG2 in open-access papers (continued):
Sharing a sentence is not in itself a finding about the gene and the disease.
Alzheimer disease (23 papers, 2012 to 2025). A progressive, neurodegenerative disease characterized by loss of function and death of nerve cells in several areas of the brain leading to loss of cognitive function such as memory and language. "While levels of proinflammatory mediators are increased, ABCB1/Abcb1 and ABCG2/Abcg2 expression and associated protein activity levels are decreased in animal models of Alzheimer’s disease as well as in patients with Alzheimer’s disease." (PMID 36973040, 2023). "ABCG2 was upregulated in the brains of Alzheimer’s patients, and the 421CC genotypes demonstrated a significantly increased predisposition to Alzheimer’s disease compared to the CA and AA alleles." (PMID 37185752, 2023). "At this point it is unclear if neuroinflammation contributes to the loss of ABCB1/ABCG2 proteins at the blood-brain barrier in Alzheimer’s disease." (PMID 36973040, 2023). "Additionally, an association between ABCG2, 421C>A and the development of Parkinson’s and Alzheimer’s diseases has been reported." (PMID 37185752, 2023). "Nevertheless, some physiological or pathological conditions have been associated with a reduction in the abundance of ABCB1 and ABCG2 at the BBB as for instance healthy ageing or Alzheimer’s disease, which may raise the risk for ABCB1-mediated DDIs at the BBB and central side effects in the elderly." (PMID 34220523, 2021). "Donepezil (DNPZ) is a cholinesterase inhibitor used for the management of Alzheimer’s disease (AD) and is dependent on membrane transporters such as ABCG2 to actively cross brain barriers and reach its target site of action in the brain." (PMID 38732233, 2024). "In brain slices from Alzheimer’s disease patients capillaries surrounding Aβ plaques have decreased ABCG2 protein levels compared with cognitive normal controls." (PMID 36973040, 2023). "ABCG2 is upregulated in neurologic diseases such as Alzheimer’s disease and amyotrophic lateral sclerosis." (PMID 38248237, 2023). "Reports about ABCG2 in Alzheimer's disease are conflicting, with different groups suggesting that it is unchanged or upregulated." (PMID 33128234, 2020). "Moreover, ABCB1 and possibly ABCG2 play a role in Alzheimer’s disease (AD) by mediating the brain clearance of beta-amyloid (Aβ) across the BBB." (PMID 33153231, 2020). "However, other groups reported increased ABCG2 protein levels at the blood-brain barrier of Alzheimer’s disease patients or found no changes at all." (PMID 36973040, 2023).
cervical cancer (22 papers, 2010 to 2025). A primary or metastatic malignant neoplasm involving the cervix. "The multidrug resistance gene ABCG2 is also an important proliferation-promoting oncogene in cervical cancer." (PMID 35534815, 2022). "The expression of ABCG2 was lower in the cervical cancer group than the normal and CIN groups (P < 0.05)." (PMID 35379200, 2022). "Other reports have also indicated that ATM, PCNA, and HMGB1 are highly expressed in cervical cancer tissues, and ABCG2 is expressed at low levels in cervical cancer tissues." (PMID 35379200, 2022). "It has been reported that SOX4 contributes to the progression of cervical cancer and the resistance to the chemotherapeutic drug through ABCG2." (PMID 32943989, 2020). "This study found that the expression of ABCG2 protein in Ect1/E6E7 cells was slightly higher than that in SiHa cells, while other studies reported that the expression of ABCG2 protein in cervical cancer was significantly higher than that in cervical intraepithelial neoplasia (CIN) tissue." (PMID 36726132, 2023). "In addition, DSF/Cu inhibited the expression of bcl2 and ABCG2 protein in two cervical cancer cell lines." (PMID 35534815, 2022). "Promoter methylation of ABCB1, ABCC1, and ABCG2 has been determined in the cervix cancer line KB-3-1 and two drug-resistant sublines, KBC-1, selected against colchicine and overexpressing ABCB1, and KB-1089, selected against the thiosemicarbazone KP1089 and overexpressing ABCC1 and ABCG2." (PMID 33066132, 2020). "The ABCG2 protein has also been found in other cervical cancer cell lines and its presence in side population cells was associated with colony forming efficiency and the capacity to proliferate producing more side population cells and differentiation to more mature cancer cells." (PMID 31320992, 2019). "The down-regulation of ABCG2 mRNA and protein was evident in cervical cancer as well." (PMID 24310600, 2011). "The downregulation of ABCG2 mRNA and protein was also evident in cervical cancer." (PMID 21188243, 2010). "In cervical cancer, the redox sensing factor Nrf2 may play an important role in the transcriptional regulation of ABCG2, and cells with upregulated Nrf2 and ABCG2 exhibit stem-like characters, including infinite cell proliferation, longevity and prevention of apoptosis." (PMID 27343550, 2017). "In vincristine-resistant human cervical carcinoma (KB-vin) cells, characterized by high ABCB1 mRNA expression and minimal expression of ABCC1 and ABCG2, β-carotene (100 μM) significantly upregulated ABCB1 mRNA levels." (PMID 41303640, 2025). "Several markers, such as Oct4, ABCG2, ALDH1, SOX2 and CD49f, were identified as CCSC-specific markers in cervical cancer cell lines." (PMID 31572058, 2019). "Several markers, such as ABCG2, ALDH1, CD133, CD49f and SOX2, were identified as CCSC-specific markers in well-known cervical cancer cell lines based on their stem-like functional probabilities in vitro." (PMID 27343550, 2017). "It has been reported that high levels of the ABC transporter protein, ABCG2, enhance the efflux capacity of SP cells for Hoechst 33342 dye and for lipophilic anti-cancer drugs, including those used for cervical cancer." (PMID 24260061, 2013). "We, therefore, have isolated and enriched cervical cancer stem like cells by sequential gating from HPV+ve and HPV‐ve human cervical cancer cell lines (SiHa, HeLa and C33a) using a set of functional and phenotypic markers (ABCG2, CD49f, CD71, CD133)." (PMID 29460395, 2018). "Moreover, in cervical cancer cells, Piwil2 overexpression also induced a significant upregulation of c-Myc, Nanog, Oct4, Sox2, and Klf4, increased the proportion of cells that were ALDH, MSCA-1, and ABCG2 positive and subsequently increased cisplatin resistance." (PMID 27602489, 2016).
epilepsy (20 papers, 2005 to 2025). A brain disorder characterized by episodes of abnormally increased neuronal discharge resulting in transient episodes of sensory or motor neurological dysfunction, or psychic dysfunction. "We assessed the role of ABCB1 and ABCG2 variants in AED resistance by comparing a uniform cohort of AED resistant MTLE-HS epilepsy patients with AED responsive JME epilepsy patients." (PMID 24586633, 2014). "Subsequently we screened three functional variants in the ABCG2 gene viz: rs2231142, rs72552713 and rs2231137 in the cohort of epilepsy patients." (PMID 24586633, 2014). "Efflux transporter ABCG2/BCRP is reported to be overexpressed in drug‐resistant epilepsy that results in decreased bioavailability of antiseizure medications (ASMs) that are its substrates." (PMID 41140058, 2025). "Our research shows that, in epilepsy, seizure-induced glutamate release activates a prostaglandin-dependent signaling pathway leading to Abcb1 and Abcg2 upregulation at the blood-brain barrier." (PMID 36973040, 2023). "Three out of these transporters, i.e., P-gp, ABCC1, and ABCG2, are mainly related to epilepsy drug resistance." (PMID 35290166, 2022). "While aging and AD showed chronic loss of certain transporters, in epilepsy a compensatory overexpression of ABCB1 and ABCG2 transporting xenobiotics and drugs out of the CNS is a common feature and appears associated with pharmacoresistance." (PMID 33916769, 2021). "In our study, patients with epilepsy and ABCG2-34AA had significantly lower V/F, and LTG elimination was relatively easier, thus resulting in lower steady-state trough concentrations of the drug." (PMID 31404235, 2019). "The results obtained from the ABCG2 ruled out the role of ABCG2 polymorphisms in determining predisposition to epilepsy." (PMID 24586633, 2014). "Further, the study also inquired the role of ABCB1 and ABCG2 in susceptibility to epilepsy by comparing the epilepsy cohorts with non-epilepsy controls." (PMID 24586633, 2014). "Many genetic polymorphisms play a role in the pathogenesis and treatment of epilepsy, e.g., SCN1A ABCG2, SCN1A, CYP3A5, and SCN2A." (PMID 39920787, 2025). "Cytokines that are upregulated in the brain of patients with epilepsy include IL1α, IL1β, IL6, and TNFα, all of which regulate blood-brain barrier ABCB1 and ABCG2." (PMID 36973040, 2023). "Allelic and genotype frequencies of the transporters MDR1, ABCG2, ABCC2, and SLC22A1 in Chinese patients with epilepsy." (PMID 31404235, 2019). "P-gp is the extensively studied transporter in epilepsy followed by multidrug resistance related proteins (MRPs, MRP1–5) and breast cancer related protein (BCRP; ABCG2)." (PMID 28264441, 2017). "The impact of other neurological diseases such as epilepsy on the expression and function of the BBB drug transporters ABCB1 and ABCG2, as well as other efflux or influx transporters, may be different." (PMID 33916769, 2021). "Although the efflux transporter, ABCG2, which codes for Breast cancer related protein (BCRP) contributes to integrity of blood brain barrier and has a considerable overlap in substrates with P-glycoprotein but pharmacogenetic data in epilepsy is scarce and inconsistent." (PMID 24586633, 2014).
Obesity (19 papers, 2019 to 2026). Accumulation of substantial excess body fat. "Here, we investigated if overweight and obesity in pregnant women altered mRNA expression of ABCB1 encoding P-gp or ABCG2 encoding BCRP in first trimester human placenta." (PMID 36997557, 2023). "A previous study using a mouse model showed that ABCG2 expression increased significantly, suggesting a link between enhanced urate reabsorption and obesity-associated HUA." (PMID 32183743, 2020). "Interestingly, certain alleles have been associated with obesity, possibly explaining the significant association of ABCG2 expression with BMI found in the present study." (PMID 40548120, 2025). "In addition, few studies have identified an association of lifestyle-related risk factors (smoking, alcohol consumption, Aspirin use) or disease conditions (hypertension, obesity) with ABCG2 rs2231142-related HUA risk." (PMID 32183743, 2020). "Thus, our results further demonstrated that cardiovascular risk factors, such as obesity, hypertension, and dyslipidemia, combined with the ABCG2 rs2231142 risk allele, greatly modified the risk of HUA and increased sUA levels." (PMID 32183743, 2020). "Diuretics inhibit OAT1/OAT3-mediated uric acid secretion, cyclosporine impairs ABCG2 function, and obesity and insulin resistance exacerbate urate retention by upregulating URAT1 expression." (PMID 40589811, 2025). "Spermatic Abcb1a, Abcb1b and Abcg2 mRNA expression also reduced in obesity." (PMID 42280472, 2026). "Furthermore, abnormalities in uric acid transporters, such as URAT1 and ABCG2, may arise with obesity, hindering proper excretion." (PMID 39463538, 2024).
liver cancer (18 papers, 2012 to 2025). An epithelial or non-epithelial malignant neoplasm that arises from the liver. "For example, future studies should verify whether ABCG2 gene knockdown mice are genetically susceptible to liver cancer and further test whether quercetin can slow the progression of liver cancer or prevent its occurrence by lowering urate levels." (PMID 40282409, 2025). "Our previous studies showed that high ABCG2 expression in liver CSCs may be the cause of high drug resistance in liver cancer." (PMID 26327240, 2015). "In terms of HCC, a recent study has proven that high SOX9 expression levels indicate tumor aggressiveness in liver cancer and enhance sorafenib resistance by modulating ATP binding cassette sub-family G member 2(ABCG2) expression." (PMID 40428248, 2025). "For example, a recent study reported that the inhibition of MDR1 or ABCG2 enabled doxorubicin to eliminate liver cancer stem cells." (PMID 38399488, 2024). "Here we explored the role of inhibition of MDR1 or ABCG2 in sensitizing liver cancer stem cells to doxorubicin, the most frequently used chemotherapeutic agent in treating liver cancer." (PMID 34031441, 2021). "Here, ABCG2-dependent stem-like side population (SP) cells, which are thought to be liver cancer stem cells (LCSCs), were present in HCC cells, and the fraction of this subset was increased in HBx-expressing HCC cells." (PMID 32168902, 2020). "Meanwhile, the direct target gene of NOTCH1, ABCG2 were also decreased in liver cancer cells which was down-regulated NAP1L1 expression." (PMID 31516385, 2019). "Furthermore, a high SOX9 expression correlates with tumor aggressiveness in liver cancer and enhances sorafenib resistance by modulating the expression of ATP-binding cassette sub-family G member 2 (ABCG2)." (PMID 40428248, 2025). "Notably, the inhibition of MDR1 or ABCG2 led to the reversal of the chemoresistance, as evident from the enhanced death of the chemoresistant liver cancer stem cells in tumorsphere-forming assays." (PMID 34031441, 2021). "Moreover, NOTCH1 and ABCG2 protein expression levels were decreased concurrent with NAP1L1 down-regulation in liver cancer cells by WB analysis." (PMID 31516385, 2019). "Since TACE is a local treatment of liver cancer, the administration of MDR1 and ABCG2 inhibitors via TACE is expected to enhance the efficacy of DOX to kill HCC while minimally affect the systemic exposure of DOX." (PMID 34031441, 2021). "The overexpression of Oct-4 in liver cancer cells induced activation of TCL1, AKT, and ABCG2 to mediate chemoresistance." (PMID 23984394, 2013). "We here report on the ABCG2 mRNA level and activity in both in vitro and in vivo models consisting of human hepatic cell lines and human samples of HCC to investigate the role of this transporter, particularly its role in drug resistance issue in liver cancer." (PMID 23153066, 2012). "This suggests that ABCG2 does not directly influence liver cancer progression but may affect liver disease pathogenesis indirectly by elevating urate levels in the kidney, subsequently impacting hepatic conditions." (PMID 40282409, 2025).
bladder cancer (16 papers, 2011 to 2025). "In a previous study, ABCG2 overexpression was linked to poor mitomycin C (MMC) responses in bladder cancer patients." (PMID 36650399, 2023). "The involvement of ABC transporters, particularly MDR1 (ABCB1), MRP1 (ABCC1) and BCRP (ABCG2), in resistance to traditional chemotherapy has been well established in bladder cancer." (PMID 39877564, 2025). "In vivo studies have shown that the downregulation of ABCG2 is a key molecular mechanism in PpIX accumulation in bladder cancer." (PMID 35886979, 2022). "In the present study, we investigated the expressions of MDR1, MRP1, MRP2, CTR1, ATP7A, ATP7B, and ABCG2 in T24 and J82 bladder cancer cells treated with emodin and cisplatin alone or in combination." (PMID 27485374, 2016). "To determine the clinical significance of our in vitro and in vivo cell line findings, we investigated the expression of ABCG2 in sections of human bladder cancer." (PMID 23226356, 2012). "Moreover, qRT-PCR and WB showed that the expression levels of stemness-associated biomarkers, such as OCT4, ABCG2 and SOX2 were markedly elevated in ATF5-overexpressed SW780 and UM-UC-3 cells, whereas reduced in ATF5-silenced bladder cancer cells." (PMID 34895217, 2021). "The roles of ABCC5, ABCA8, ABCC10, ABCB10, ABCG1, ATP7B, ABCG2, and mitochondrial SLC25A10 in platinum-receiving urinary bladder cancer patients should be the subject of further investigation." (PMID 36650399, 2023). "In previous studies, ABCG2, CD44, and CD133 were used to identify and isolate the bladder cancer stem cells." (PMID 33363019, 2020). "We measured the mRNA expressions of MDR1, MRP1, MRP2, ABCG2, CTR1, ATP7A, and ATP7B in T24 and J82 bladder cancer cells in different groups." (PMID 27485374, 2016). "We show that ABCG2 expression correlated with NMIBC recurrence and progression, and that ABCG2 expression is, in part, regulated by MAPK activity and this correlates with ours and published findings of activated ERK predicting poor prognosis in bladder cancer." (PMID 23226356, 2012).
sarcoma (16 papers, 2008 to 2022). A usually aggressive malignant neoplasm of the soft tissue or bone. "High expression of ABCG2 was detected in CSCs isolated from undifferentiated pleomorphic sarcoma (UPS) cell line." (PMID 32532153, 2020). "Co-expression of nestin, CD133 and ABCG2 as putative CSC markers has been studied in different type of sarcomas." (PMID 31983166, 2020). "Moreover, it has been reported that ABC transporters, especially MRP-1 (ABCC1), ABCG2 and P-gp (ABCB1), are associated with worse prognosis in sarcomas, since these pumps mediate multidrug resistance mechanisms." (PMID 32532153, 2020). "Interestingly the ALDH1high population of all sarcoma cell lines demonstrated, with statistic significance, increased expression levels of ABCG2 compared to control or ALDH1low cells, whereas the p value for ABCA2 was not significant." (PMID 22928012, 2012). "In the present study, ABCG2 was upregulated in ALDH1high cells from all three sarcoma cell lines." (PMID 22928012, 2012). "Analysis of disease-free survival (DFS) shows a correlation between low ABCG2 expression and poor prognosis for CESC (p = 0.029), LUAED (p = 0.010), sarcoma (SARC) (p = 0.047), and thyroid carcinoma (THCA) (p = 0.009)." (PMID 36555598, 2022). "Similar results were reported in pediatric sarcomas, where high expression of CD133 and nestin, but not of ABCG2, were associated with shorter survival in RMS and EWS patients, supporting the potential prognostic value of CD133 in sarcomas." (PMID 32532153, 2020). "Others have also investigated the effects of single-step doxorubicin selection on the human sarcoma cell line MES-SA and have reported an increase in ABCB1 expression; yet previous studies were performed before the identification of ABCG2 as a major ABC transporter in the area of MDR." (PMID 18382425, 2008). "ABCG2 may not be enriched in sarcomas, which would explain this result." (PMID 28212529, 2017). "Moreover, in the analysis of undifferentiated pleomorphic sarcoma subgroup we demonstrated the negative correlation for the ABCB1 and ABCG2 expression and SI (Doc) or SI (Gem + Doc)." (PMID 35328603, 2022).
cystic fibrosis (15 papers, 2005 to 2025). Autosomal recessive disorder caused by pathogenic variants in the CFTR gene (cystic fibrosis transmembrane conductance regulator), which encodes a chloride and bicarbonate channel expressed in epithelial cells, and follow the diagnosis criteria. "There are parallels between ABCG2 141K and the important cystic fibrosis-causing gene variant, ΔF508 in CFTR, also an ABC transporter." (PMID 32164793, 2020). "Accumulation of aggresomes is a feature of both ABCG2 141K and cystic fibrosis, indicative of impaired and/or inadequate protein degradation." (PMID 32164793, 2020).
epidermoid carcinoma (15 papers, 2008 to 2025). "We have shown earlier that the human epidermoid carcinoma cell line A431 provides a reliable and stable model for the characterization of the function of MDR ABC transporters ABCB1 and ABCG2." (PMID 30863990, 2019).